ETS2 (ETS proto-oncogene 2, transcription factor)
Diseases named in the same sentence as ETS2 in open-access papers (continued):
Sharing a sentence is not in itself a finding about the gene and the disease.
rheumatoid arthritis (2 papers, 2021 to 2024). A chronic, systemic autoimmune disorder characterized by inflammation in the synovial membranes and articular surfaces. "ETS2 is a ubiquitous transcription factor activated after phosphorylation at threonine-72 residue and its active form induces the molecular reprogramming of rheumatoid arthritis synovial fibroblasts (RASFs) to osteoclast-like cells that contribute to cell population heterogeneity in the synovium." (PMID 38867295, 2024).
Stroke (2 papers, 2014 to 2025). Sudden impairment of blood flow to a part of the brain due to occlusion or rupture of an artery to the brain. "Along with Fos and Jun, Cebpb, Ets2, Egr1, and Junb were enriched in Neut_Gngt2 and Neut_Cd14, particularly after stroke." (PMID 39930981, 2025). "miR-320 targets ETS2, a transcription factor that regulates the expression of several genes important to leukocyte extravasation post-stroke including MMP-9, MMP-3, MMP-13, ANGPT1, and TNF." (PMID 24911610, 2014).
type 2 diabetes (2 papers, 2009 to 2016). "Recently, it was shown that cardiomyocytes mediate anti-angiogenic effects in type 2 diabetic rats via the exosomal transfer of miR-320 into endothelial cells where its angiogenesis-related target genes (IGF-1, Hsp20 and Ets2) were down-regulated." (PMID 26930277, 2016). "Our study now provides evidence that in vivo and in vitro the number of VPC is reduced in conditions of type 2 diabetes and that one major signalling pathway involved is the activation of the transcription factors ETS1 and ETS2." (PMID 19225563, 2009).
acute respiratory distress syndrome (1 paper, 2022). Progressive and life-threatening pulmonary distress in the absence of an underlying pulmonary condition, usually following major trauma or surgery. "For instance, in terms of LPS-triggered inflammation of acute respiratory distress syndrome (ARDS), miR-381-3p presents a low expression, and KCNQ1OT1 silencing inhibition may attenuate LPS-caused ARDS inflammation via up-regulating miR-381-30 and modulating ETS2." (PMID 35246016, 2022).
adenomyosis (1 paper, 2022). The growth of endometrial tissue inside the muscular wall of the uterine corpus. "Similarly, the PGR-repressed genes Gadd45a, Ets2, Vstm4 and C1qtnf6 may be important genes related to progesterone resistance-mediated mechanisms of adenomyosis development." (PMID 35563206, 2022).
benign papillomas (1 paper, 2015). "Conversely, morphological and biochemical features of benign papillomas were enhanced in HRasG12V; Tgfbr2-null tumor masses in the absence of ETS2." (PMID 26590320, 2015).
cervical cancer (1 paper, 2009). A primary or metastatic malignant neoplasm involving the cervix. "Increased expression of Ets2 has been associated with initiation and progression of various cancer types and its expression was altered in cervical cancer cell lines due to chromosomal changes in 21q22.1–22.2 where human ETS2 resides." (PMID 19152694, 2009).
choroidal melanoma (1 paper, 2008). Malignant tumor of melanocytes of the choroid. "One role for ETS-1 and ETS-2 in ocular cancer and choroidal melanoma may be mediated through their increased transcriptional activity and upregulated expression of their target genes involved in angiogenesis and/or metastatic propagation." (PMID 18958307, 2008). "Indeed, microarray gene expression profiling analysis by Harbour and Onken (and personal communication) showed that ETS-2 mRNA levels in human choroidal melanoma were four times higher than those in adult normal melanocytes." (PMID 18958307, 2008). "Thus, ETS-1 and ETS-2 may be involved in the development of this disease and are therefore potential targets for choroidal melanoma gene therapy." (PMID 18958307, 2008). "In conclusion, this study shows that ETS-1 and ETS-2 may play a major role in choroidal melanoma." (PMID 18958307, 2008). "Therefore, upregulation of ETS-1 and ETS-2 could also occur in choroidal melanoma." (PMID 18958307, 2008).
Cirrhosis (1 paper, 2022). A chronic disorder of the liver in which liver tissue becomes scarred and is partially replaced by regenerative nodules and fibrotic tissue resulting in loss of liver function. "Several oncogenic transcription factors (TFs) inferred with DoRothEA35 including FOS, ETS2, RELB, SOX10, ERG, WT1 and JUND and TFs supporting stemness such as PBPJ and ARID3A were upregulated in cirrhosis patients and correlated with bacterial translocation." (PMID 35803930, 2022).
colitis (1 paper, 2023). Inflammation of the colon. "Further studies using acute/chronic colitis and colitis-associated cancer models with genetic perturbation of ETS2 will clarify its contribution to inflammation-driven cancer." (PMID 36609474, 2023).
colorectal adenoma (1 paper, 2023). An adenoma that arises from the colon or rectum. "Moreover, ETS2 expression was increased in colorectal adenoma, indicating that it is likely to be involved in the early development of CRC." (PMID 36609474, 2023).
dementia (1 paper, 2023). Loss of intellectual abilities interfering with an individual's social and occupational functions. "Five autoantibodies (CAMK2A, CKS1B, ETS2, MAP4, and NUDT2) were dysregulated in both dementia and MCI." (PMID 38107644, 2023). "Five autoantibodies in particular, were dysregulated in dementia and MCI, including CAMK2A, CKS1B, ETS2, MAP4, and NUDT2." (PMID 38107644, 2023). "Five autoantibodies were commonly dysregulated in both dementia and MCI, including anti-CAMK2A, CKS1B, ETS2, MAP4, and NUDT2." (PMID 38107644, 2023). "Two of the negatively correlated autoantibodies, ETS2 and ODF3, were dysregulated in dementia, and three were dysregulated in MCI." (PMID 38107644, 2023).
diabetic retinopathy (1 paper, 2023). "In diabetic retinopathy, this may indicate that Ets2 is involved in pathological processes." (PMID 37423944, 2023).
endotoxemia (1 paper, 2019). "We first found that compared to wild-type mice, Ets2-deficient mice showed higher levels of IL-6 and TNF-α after LPS challenge, indicating the crucial role of Ets2 in attenuating inflammation in mouse endotoxemia." (PMID 31785145, 2019).
epilepsy (1 paper, 2021). A brain disorder characterized by episodes of abnormally increased neuronal discharge resulting in transient episodes of sensory or motor neurological dysfunction, or psychic dysfunction. "It should be noted, however, that the ETS expression profile is also different in epilepsy; ELF1, ELK1, ELK4, ETS1, ETS2, and ETV1 are expressed at higher levels than ELF4, ELK3, and ETV4, and there is also variability in expression among different types of epilepsy." (PMID 33671331, 2021).
esophageal adenocarcinoma (1 paper, 2023). A malignant tumor with glandular differentiation arising predominantly from Barrett mucosa in the lower third of the esophagus. "High ETS2 expression was associated with long OS in LIHC (HR = 0.58, 95% CI: 0.41-0.82), UCEC (HR = 0.56, 95% CI: 0.36-0.86), esophageal adenocarcinoma (EAC; HR = 0.42, 95% CI: 0.21-0.83), KIRC (HR = 0.75, 95% CI: 0.52-0.95), and THYM (HR = 0.24, 95% CI: 0.05-0.93)." (PMID 36760475, 2023).
esophageal cancer (1 paper, 2015). A primary or metastatic malignant neoplasm involving the esophagus. "However, with the exception of a report of an elevation in Ets2 in ~75% of esophageal cancer patients, an association of ETS proteins and SCCs has not been hitherto described, and functional analyses in SCCs are entirely lacking for this family." (PMID 26590320, 2015).
fractures (1 paper, 2022). "The signals in the other four genomic loci associated with hip fractures (REST, HOXC8, SALL1, and ETS2) were previously shown to associate with different BMD measures, supporting the notion that BMD is an important determinant also of hip fracture risk." (PMID 36260985, 2022).
gastric adenocarcinoma (1 paper, 2017). "ETS2 and Siah1 were assessed in gastric adenocarcinoma, antral biopsy samples (stage III, rapid urease test-positive) collected from consenting patients." (PMID 28481365, 2017).
gastric tumors (1 paper, 2019). "In the gastric tumors, many of these genes are regulated by ETS2, BMP4, and TGFB1 and by the kinases MAPK1(ERK) and CCNK and the transcription regulators E2F, CBX5, and CCND1." (PMID 31584998, 2019).
HIV-1 infection (1 paper, 2017). The type species of lentivirus and the etiologic agent of acquired immunodeficiency syndrome (AIDS). "The identification of Ets-2 as transcriptional silencer of the HIV-1 virus sets the stage for investigations into the immunopathogenesis of the HIV-1 infection in the domain of genomic conflict." (PMID 29354130, 2017). "It would be interesting to investigate whether Ets-2 expression levels in naive Th cells affect the progression of HIV-1 infection in progressors vs elite controllers." (PMID 29354130, 2017).
Liver fibrosis (1 paper, 2025). "Liver fibrosis was induced in WT and HSC-specific Ets1-KO (Ets1ΔHSC) and Ets2-KO (Ets2ΔHSC) mice by administration of CCl4 for 6 weeks, followed by cessation of liver injury for 2 weeks." (PMID 41196693, 2025).
mastitis (1 paper, 2009). Inflammation of breast tissue during lactation or postpartum due to an obstructed duct or infection.
mesothelioma (1 paper, 2013). A usually malignant and aggressive neoplasm of the mesothelium which is often associated with exposure to asbestos. "In another study, they showed that transient expression of Ets-2 protect cells from apoptosis by increasing the promoter activity of Bcl-xl and consequently enhancing its mRNA and protein expression levels in mesothelioma cell lines." (PMID 24069250, 2013).
myeloid leukemia (1 paper, 2021). A clonal proliferation of myeloid cells and their precursors in the bone marrow, peripheral blood, and spleen. "Also, the high expression of ETS2 predicted a poor prognosis in severe myeloid leukemia." (PMID 34178996, 2021).
ocular cancer (1 paper, 2008). A benign or malignant neoplasm affecting the structures of the eye. "We previously showed that the transcription factors, ETS-1 and ETS-2, were both upregulated from P20 to three months in our ocular cancer model." (PMID 18958307, 2008). "This is consistent with previous studies that demonstrated the fact both ETS-1 and ETS-2 may play important roles in the development of ocular cancer." (PMID 18958307, 2008).
osteomyelitis (1 paper, 2023). An acute or chronic inflammation of the bone and its structures due to infection with pyogenic bacteria. "Upon further validation, we identified 3 TFs highly expressed in osteomyelitis and DFU, including CRBPB, ETS2, and STAT3." (PMID 37904457, 2023). "We further found that 3 TFs, including CRBPB, ETS2, and STAT3 were highly expressed in both osteomyelitis and DFU." (PMID 37904457, 2023).
pneumonitis (1 paper, 2024). An inflammatory process affecting the lung parenchyma. "Indeed, in mice with severe macrophage-induced pneumonitis, the prevention of Ets-2 phosphorylation results in decreased tissue macrophage infiltration." (PMID 39505854, 2024).
pulmonary fibrosis (1 paper, 2023). Chronic progressive interstitial lung disorder characterized by the replacement of the lung tissue by connective tissue, leading to progressive dyspnea, respiratory failure, or right heart failure. "Previous studies highlighted the importance of phosphorylated Ets2 in lung inflammation and extracellular matrix remodeling, pathways involved in pulmonary fibrosis." (PMID 36681830, 2023).
renal fibrosis (1 paper, 2022). A final common manifestation of a wide variety of chronic kidney diseases characterized by glomerulosclerosis and tubulointerstitial fibrosis. "Also, deletion of ETS2 in pancreas leads to fibroblast continuous activation, however, studies in kidney showed that ETS2 could promote epithelial-to-mesenchymal transition and cause the progression of renal fibrosis." (PMID 35372448, 2022).
skin cancer (1 paper, 2016). "Here, we found that Ets2 dosage had a small positive effect on TPA-induced proliferation of Ts1Rhr keratinocytes, a fundamental step in progression of skin cancer." (PMID 26752700, 2016).
squamous cell carcinoma (1 paper, 2019). A carcinoma arising from squamous epithelial cells. "For example, Ets2 and Elk3 genes in squamous cell carcinoma can upregulate specific SEs." (PMID 31105558, 2019).
tumor (99 papers, 2004 to 2026). "Recent studies have highlighted key factors in the progression of THCA, like ETS2, a transcriptional regulator implicated in tumor development and metastasis in various cancers." (PMID 40938895, 2025). "In PC, ETS2 expression is closely linked to tumor progression, potentially influencing cell proliferation and apoptosis through the regulation of cell cycle-related genes." (PMID 41203621, 2025). "An additional human scRNA-seq dataset originating from 28 GB tumours further confirmed the expression of ID2 and ETS2 genes in tumour-associated microglia/macrophages in the context of GB tumours." (PMID 39019900, 2024). "ID2 and ETS2 genes were found to be expressed by the tumour-associated microglia isolated from human GB tumour biopsies." (PMID 39019900, 2024). "As a transcription factor, ETS2 is responsible for the transcriptional regulation of a variety of tumor-associated genes, such as Cyclin D1." (PMID 34261460, 2021). "Multiple studies with cell lines and animal models suggest that Ets2 causally exhibit both tumor-promoting and tumor-suppressive effects in distinct carcinomas." (PMID 27556183, 2016). "Various genes specifically expressed in BMDCs have been associated with tumor aggressiveness such as Ets2, Vegf, Hif1α, and Atf-3." (PMID 26497998, 2015). "Hence, the transcription factor ETS2 revealed itself as a key regulator of macrophage functions associated with tumour suppression." (PMID 39019900, 2024). "Notably, ETS2 rs461155A>G was significantly associated with decreased ETS2 mRNA expression in both tumor and paired normal tissues (Ptrend = 4 × 10−7, and 3 × 10−4, respectively)." (PMID 26893365, 2016). "Notably, ETS2 rs461155A>G was significantly associated with decreased ETS2 mRNA expression in both tumor and paired normal lung tissues (Ptrend = 4 × 10−7, and 3 × 10−4, respectively)." (PMID 26893365, 2016). "In addition, we also found that the expression level of ETS2 gene in tumor tissues was negatively associated with survival, indicating that the lower the expression of this gene, the higher would be the chance of death." (PMID 25575813, 2015). "Notably, genotyping of the single tumor that grew from E1− E2−/HrasG12V cells demonstrated that it contained the Ets2flox allele, and therefore still expressed ETS2." (PMID 24968297, 2014). "Additionally, Ets2 deficiency in tumor fibroblasts significantly impaired angiogenesis in vivo in matrigel plug assays." (PMID 23977064, 2013). "These comprised two truncating pathogenic variants—RB1 R255* and TSC1 R786*, one missense probable damaging variant—VHL tumor suppressor R58W, and four splice variants of unknown significance in ETS2 transcription factor, SGK1 serum/glucocorticoid regulated kinase 1, AXL RTK and MIB1." (PMID 31258848, 2019). "Methylation of one CpG site in our region 9 has previously been shown to interfere with binding of the ETS2 transcription factor and ER expression was negatively correlated with methylation at this site in ER‐positive tumours." (PMID 39108022, 2025). "This study identified the cellular senescence gene ETS2 as a tumor suppressor in THCA, which interacts with ZMYND11 to regulate THCA tumor progression through the mTOR pathway, thereby inhibiting cell senescence." (PMID 40938895, 2025). "The results showed that, compared with the control group, tumors derived from the ETS2 overexpression group exhibited a significantly reduced weight, indicating that ETS2 inhibits tumor growth in vivo." (PMID 40938895, 2025). "In vivo, ETS2 overexpression reduced tumor growth and increased ETS2 and ZMYND11 expression in xenograft tumors." (PMID 40938895, 2025).